CAV2 (caveolin 2)
Diseases named in the same sentence as CAV2 in open-access papers (continued):
Sharing a sentence is not in itself a finding about the gene and the disease.
cancer (continued). "The interaction between miRNA-199a-3p and CAV2 may provide an interesting target for intervention in cancer." (PMID 26112043, 2015). "CAV2 has been shown to be a target of miRNA-199a-3p with over-expression of CAV2 inhibiting the effect exerted by miRNA-199a-3p in promoting proliferation, survival and sensitivity of cancer cells to anticancer drugs." (PMID 26112043, 2015). "However, in previous gene expression profiling studies, CAV1 and CAV2 were shown to be expressed at higher levels in normal breast-like cancer." (PMID 18612310, 2008). "Prompted by indications that Cav2+ nerve interactions may precipitate an enhanced mitochondrial respiratory phenotype within cancer cells, we conducted an evaluation of the mitochondrial respiratory functions in HNSCC cells co-cultured with either Cav2-knockout or wild-type TGs." (PMID 41330921, 2025). "However, higher levels of CAV2 in T7 CAMs could be interpreted as a sign of increased activation of the endothelium due to the presence of cancer cells." (PMID 29662633, 2018). "A 2011 study investigated how Caveolin-2 (CAV2) can affect cell proliferation and intracellular signaling in various cancer types." (PMID 40862737, 2025). "Analysis of mRNA expression in TCGA paired samples revealed notably enhanced levels of LDHA, SHC1 and CDKN3 in cancer tissues compared to adjacent tissues, whereas PCSK9, BTK, CAV2 and PDGFB showed significantly reduced expression." (PMID 40182622, 2025). "This alludes to the intriguing possibility that Cav2-expressing nerves and CGRP-expressing nerves affect metabolic alterations within cancer cells via different mechanisms." (PMID 41330921, 2025). "An in-depth analysis of The Cancer Genome Atlas (TCGA) datasets underscores the prominence of caveolin-2 (CAV2) as a top prognostic indicator for HNSCC5, a cancer known for its widespread innervation by both sensory and adrenergic neural networks." (PMID 41330921, 2025). "Upregulation was observed in many genes, including CAV2, FGFBP1, KRT19, MST1R, OCLN, and RGS2, which play important roles in the negative regulation of EMT and metastasis phenotypes in many cancers." (PMID 37298519, 2023). "We further explored the expression levels of CAVs in another independent data set (TIMER database) and validated that CAV1, CAV2, and CAV3 were expressed low in most cancer, especially in BC." (PMID 36147736, 2022). "Changes in DRD3 levels along with GDNF, GNAL, HRH2, CAV2, and DLG4 were characteristic of G1 cancer." (PMID 34768458, 2021). "Three proteins, CAV1, CAV2, and RAGE, were higher in all control tissues as compared to corresponding cancer tissues." (PMID 26930711, 2016). "Regarding caveolin-2 there are not really clear evidences about a possible role that it plays in cancer." (PMID 18949068, 2007). "However, our observations indicate that Cav2+/+ TG co-cultures foster an enhanced proliferation of cancer cells compared to Cav2-/- TG co-cultures, regardless of 2-DG conditions." (PMID 41330921, 2025). "Interestingly, unlike CAV1, the level of CAV2 mRNA was also increased in the majority of basal-like cancer." (PMID 18612310, 2008). "Immunohistochemical assays showed that the expression of both caveolins was more abundant in the myoepithelial cells of the mammary duct than ductal epithelial cell in normal breast tissues, while fewer expressions of CAV1 and CAV2 proteins were detected in cancer tissues (data not shown)." (PMID 15305200, 2004). "The lack of these cancer stem cell markers, specifically SEMA5A (semaphorin 5A), KITL (KIT ligand, stem cell factor), CAV2 (caveolin 2), EPS8 (epidermal growth factor receptor pathway substrate 8) and PKP4 (plakophilin 4), was associated with acquired resistance to radiation in this study." (PMID 33767581, 2021).
cancer (continued). "Several other candidate genes were found to be undetectable in whole blood, while most of the genes that were detectable (EGLN3, CAV2, ESM1, TMEM45A, NOL3, FABP7) did not exhibit significant dysregulation in expression between cancer and healthy PAXgene samples." (PMID 32013938, 2020).
infection (24 papers, 2004 to 2025). The state of being infected such as from the introduction of a foreign agent such as serum, vaccine, antigenic substance or organism. "Additionally, as a recombinant viral vector, CAV2 provides a safe and long-term protective effect in veterinary fields that reduced the natural infection risk." (PMID 29228675, 2017). "The previously established singlex PCR assay identified CDV DNA in 14 samples (25%) as a single infection, 2 samples (3.63%) with CAV-2 and 1 sample (1.8%) was detected for Bb." (PMID 41394100, 2025). "Increased red fluorescence over time in the OS cells in comparison to the NCFs indicated conditional replication and the release of CAV2-AU-M2 for further infection into the neighboring cells." (PMID 38391964, 2024). "Infection with CAV2-AU-M2 (100 MOI) resulted in an increased red fluorescence by 72 h in the OS cells compared to the non-infected cells (0 MOI) and NCF cells." (PMID 38391964, 2024). "To better understand CAV2 tropism, we analyzed infection patterns of CAV2 and Ad5 using replication-incompetent vectors expressing green fluorescence protein (GFP) CAVGFP and Ad5GFP, respectively." (PMID 36591003, 2022). "In contradistinction, CF11 with low levels of CAR, yet high levels of infection with Ad5 and moderate levels of infection with CAV2, suggests that a relatively low expression of CAR is needed for Ad5 infection." (PMID 36591003, 2022). "We employed AAV2retro-hSyn-FLPo-T2A-GFP rather than CAV2-FLPo for the PVH → LPBN projection, because we found that AAVretro is more efficient in retrograde infection than CAV2 at this projection." (PMID 32265438, 2020). "We carried out a viral injection screen and found that intravenous Canine Adenovirus 2 (CAV2) preferentially targeted perivascular astrocytes throughout the adult brain, with sparing of the hippocampal hilus from infection." (PMID 29335006, 2018). "To determine the cortical layer(s) in which IL→PreL (or PreL→IL) terminate within the respective other cortical area, we applied combinatorial infection of CAV2-Cre and AAV9-flex-synaptophysin-Myc to infect these neurons, visualizing their synaptic terminals." (PMID 30006525, 2018). "It has been shown that CAV2 infection is mediated via interaction with cell membrane-bound Coxsackie Adenovirus Receptor (CAR)." (PMID 29335006, 2018). "Four weeks after CAV2-cre injection, we observed EYFP-expressing neurons or GFP-expressing neurons in both sides of the ACC in Ai32 or Ai35 mice, indicating the stable infection of CAV2-cre on ACC-spinal cord projecting neurons." (PMID 29760484, 2018). "Piglets infected with Salmonella show an increase of miR-29a 3 days post-infection, which correlates with a decreased expression of its targets Cdc42 and Cav-2 both at transcript and protein levels." (PMID 29250058, 2017). "In the present study, we aimed at a quantitative analysis of metabolic fluxes in E1-transformed MDCK cells growing as adherent cultures and after infection by CAV2." (PMID 27004747, 2016). "In a variety of human cell lines, caveolin-2 forms a heterodimer with caveolin-1, which after infection with P. aeruginosa, co-localizes with CFTR and P. aeruginosa." (PMID 26047157, 2015). "We conclude that described dynamics are the reason why significant CAV2 dysregulation is shown only at 3 d p.i., where re-infection and colonisation effects are present and all infected subjects are Salmonella positive." (PMID 23826261, 2013). "We also analysed potential effects of miR-29a as well as siRNA directed CAV2 modulation on Salmonella invasion of intestinal epithelia using HT-29 as an in vitro infection model." (PMID 23826261, 2013). "RT-qPCR experiments verified up-regulation of miR-29a after infection while its predicted target Caveolin 2 was significantly down-regulated as examined by transcript and protein detection." (PMID 23826261, 2013).
infection (continued). "Cav-2 has been shown to facilitate infection of murine lung epithelial cell line MLE-12 with Pseudomonas aeruginosa and that lipid raft targeting and tyrosine phosphorylation of Cav-2 as well as interaction with Csk and c-Src was important." (PMID 22229094, 2011). "Pathogen-containing vacuoles of each of the strains indeed were unable to acquire caveolin-2 when the EBs had been inactivated by UV irradiation prior to infection." (PMID 15271223, 2004). "Our data showed that CAV2-AU-M2 demonstrated a noticeable decrease in cell confluence in two OS cell lines due to the induction of cytotoxic processes and an increase in virus spread and infection." (PMID 38391964, 2024). "Additionally, why are certain brain regions seemingly protected against infection from bloodborne CAV2 particles?" (PMID 29335006, 2018). "Cav-2−/− mice could be used to better understand the effect of Cav-1 and Cav-2 on pathogen infection." (PMID 29250058, 2017). "Additional infection experiments were performed with HT-29 transiently overexpressing CAV2." (PMID 23826261, 2013). "Skin-migrated DCs were significantly transduced by CAV2 in vitro, contrasting with the refractory state of human monocyte derived-DCs (Mo-DCs) to CAV2 transduction, when used at similar multiplicity of infection." (PMID 23300693, 2012). "In addition, although there is a single report of a CAV-2 sequence being detected by PCR in the faeces of a red fox13, there is no definitive evidence to suggest that CAV-2 is a frequent infection or causes disease in this species." (PMID 27796367, 2016). "Aside from a general upregulation of cellular carbon metabolism upon infection, we have uncovered specific pathways that play a prominent role for effective CAV2 replication and which could be explored as targets in future optimization of production processes of canine adenoviral vectors." (PMID 27004747, 2016). "Knockdown of additional host factors, particularly caveolin-2 (CAV2), led to a notable reduction in infection by approximately fourfold, suggesting the involvement of caveolae as entry mechanism for HIV-1 into MDDCs that has already been previously reported (26, –, 28)." (PMID 40029073, 2025). "Therefore, we have evaluated CAV2 and Ad5 (CAV2GFP, Ad5G/L) infection patterns in various canine and human cell lines to determine their different tropisms." (PMID 36591003, 2022). "This CAR-tropic nature of CAV-2 is further supported by the lack of infection of cells in CAR CNS-KO mice." (PMID 32581729, 2020). "Although our replication-dependent assays indicate a requirement for caveolin 2 (CAV2) for infection, this protein was shown not to be involved in virus entry using our fusion assay." (PMID 25375324, 2014). "siRNA-mediated downregulation of proteins involved in caveolae-mediated endocytosis revealed that CAV2, but not the other proteins analyzed are important for infection with MHV (light blue)." (PMID 25375324, 2014). "For validation of outlined interactions and to legitimate calculated miR-29a-target interactions and to prove biological significance, we examined the expression of miR-29a, AKT3, BAIAP2, COL4A1, VCL, CAV2 and CDC42 over the course of infection by means of RT-qPCRs." (PMID 23826261, 2013). "Caveolin-1 and Cav-2 also show opposing effects regarding infections by the Gram-negative bacteria Pseudomonas aeruginosa, although one may observe that disparate results were obtained in in vivo studies of Pseudomonas infection, as it will be discussed next." (PMID 29250058, 2017). "To confirm that chlamydial inclusions indeed could acquire caveolin-2 independently of caveolin-1, we further examined infections using caveolin-1 negative FRT cells." (PMID 15271223, 2004).
infection (continued). "Intravenously-delivered CAV2 may enter astrocytes preferentially via exosomes delivered across endothelial cells, while direct injection of CAV2 into the brain parenchyma may result in direct infection of cells without the formation of exosomes, which could potentially explain this difference." (PMID 29335006, 2018).
neurological disorders (4 papers, 2014 to 2025). "Inhibiting high-voltage-activated calcium channels (HVACCs; CaV1/CaV2) is therapeutic for myriad cardiovascular and neurological diseases." (PMID 31403402, 2019). "Since NMDA receptor channels and Cav2 channels play essential roles in synaptic transmission of the CNS, TRPV4 may be a better target for both the prevention and treatment of mTBI and related neurological disorders." (PMID 41024271, 2025).
kidney disease (1 paper, 2017). "The repressive effect of H2O2, especially on caveolin-2/CAV2, PTRF/CAVIN1 and SDPR/CAVIN2 protein levels and the lack of effect on caveolin-1/CAV1 protein, argued against a major role of oxidative stress in induction of caveolar proteins in kidney disease." (PMID 29065889, 2017).
neurodegenerative disease (1 paper, 2023). A disorder of the central nervous system characterized by gradual and progressive loss of neural tissue and neurologic function. "Beyond the role of caveolin-1, some studies have shown that caveolin-2 may play roles in neurodegenerative diseases, particularly AD." (PMID 38067108, 2023). "Besides caveolin-1, caveolin-2 has been also found to facilitate leukocyte infiltration in brain ECs, contributing to the development of common neurodegenerative diseases." (PMID 38067108, 2023).
CAV2 also shares sentences with these, for which no sentence is quoted: primary open-angle glaucoma (4 papers); epilepsy (2); viral infections (2); acute lung injury (1); autism spectrum disorder (1); benign prostatic hyperplasia (1); carcinoid tumor (1); cardiovascular diseases (1); cervical cancer (1); channelopathy (1); colorectal cancer (1); cutaneous melanoma (1); esophageal squamous cell carcinoma (1); essential thrombocythemia (1); exfoliation glaucoma (1); fibrosis (1); foot and mouth disease (1); gastric cancer (1); hypopharynx cancer (1); idiopathic pulmonary fibrosis (1); Intellectual disability (1); invasive ductal breast carcinoma (1); large cell lung carcinoma (1); leiomyoma (1); lentivirus infection (1); Lewis lung carcinoma (1); liposarcoma (1); Lymph Node (1); neuroblastoma (1); ocular hypertension (1).
A further 9 diseases each share a sentence with CAV2 in 1 paper.